ZNNT1 (ZNF706 neighboring transcript 1)
Synonyms: AP003469.4
Gene: Long non-coding RNA gene on chromosome 8 (101,166,805 to 101,169,629, reverse strand). Ensembl gene ENSG00000261087.
Diseases named in the same sentence as ZNNT1 in open-access papers:
ZNNT1 is named in the same sentence as 5 diseases in open-access papers, as found by Europe PMC text mining. Sharing a sentence is not in itself a finding about the gene and the disease. The quoted sentences say what the papers report.
uveal melanoma (5 papers, 2020 to 2024). A melanoma derived from melanocytes of the uveal tract. "For example, the lncRNA ZNF706 neighboring transcript 1 (ZNNT1) is expressed at a low level in uveal melanoma cells, and ZNNT1 promotes autophagy by upregulating ATG12 expression, and thus has a tumor suppressive effect." (PMID 38481525, 2024). "Another lncRNA called ZNF706 Neighboring Transcript 1 (ZNNT1) plays role as potential tumor suppressor in uveal melanoma." (PMID 35309939, 2022). "The autophagy-induced ZNNT1 acts as a protective factor against uveal melanoma." (PMID 38773560, 2024).
colon cancer (1 paper, 2023). "Our findings suggest that ZNNT1 may be a promising molecular target for the therapy of colon cancer." (PMID 37448957, 2023).
hepatocellular carcinoma (1 paper, 2026). A malignant tumor that arises from hepatocytes. "In hepatocellular carcinoma, METTL16 and METTL3 collaborate to enhance m6A modifications on ZNF706 neighboring transcript 1 (ZNNT1) mRNA, thereby increasing its stability and expression." (PMID 41459114, 2026).
melanoma (1 paper, 2024). A malignant, usually aggressive tumor composed of atypical, neoplastic melanocytes. "In vivo tests demonstrated that ZNNT1 could stop melanoma from growing in naked mice, and that ZNNT1's tumour suppressor effect could be somewhat mitigated by knocking down ATG12." (PMID 38467935, 2024).
tumor (5 papers, 2021 to 2024). "One study reported that the overexpression of lncRNA ZNNT1 can promote ATG12-dependent cell death to inhibit UM tumor cell growth and migration." (PMID 36544483, 2022). "For example, a recent research reported that lncRNA ZNNT1 could act as a tumor inhibitor in UM by upregulating ATG12 gene expression, indicating delicate interactions between lncRNAs and autophagy." (PMID 33868366, 2021).